CYP1A1 (cytochrome P450 family 1 subfamily A member 1)
Diseases named in the same sentence as CYP1A1 in open-access papers (continued):
Sharing a sentence is not in itself a finding about the gene and the disease.
tumor (continued). "Comparing tumor cells (B-CPAP cell line) and normal cells (Nthy-ori 3-1 cell line), the expression levels of model genes (PAPSS2, ITPKA and CYP1A1) were as expected." (PMID 36685893, 2022). "Polydatin inhibited the protein expressions of AHR, CYP1A1, and HSP-90, which are tumor grade-related markers, and the IC50 concentration of polydatin was 20 μM." (PMID 34577602, 2021). "The mRNA expression of CYP1A1 (p = 0.002), CCL20 (p = 0.047), p19 (p = 0.029), CCL19 (p = 0.013), IL-36γ (p = 0.0076), and IL-17 (p = 0.0035) was significantly decreased in tumor from AhR-(fl/fl) Krt5-(Cre) mice compared with wild type mice." (PMID 33178182, 2020). "A cut-off point for relative expression of AHR and cytochrome 450 enzymes (CYP1A1, CYP1A2, and CYP1B1; markers of AHR activation) was determined to compare with the grade, stage, and tumor progression." (PMID 32907554, 2020). "Significant induction of CYP1A1 and CYP2W1 protein and mRNA expressions was demonstrated in homogenates of MKN‐45 tumours 24 hours after treatment of mice with 5F 203 (5 mg/kg, ip)." (PMID 31876059, 2020). "The results proved that apigenin and luteolin inhibited MMP1 expression and CYP1A1 activity, which trigger the retraction of the adjacent LEC barrier thereby enabling MDA-MB231 tumor spheroid intravasation." (PMID 29593542, 2018). "UVB-induced AhR activation upregulates suppression of reversible tumor promotion before tumor the RAF-MEK1/2-ERK1/2 signaling pathway via c-Src-dependent EGFR activation, and when AhR is activated, it upregulates its specific target gene, cyp1a1." (PMID 29285309, 2017). "Unsupervised hierarchical clustering analysis based on methylation pattern had identified two tumor clusters, which significantly differ by CpG island methylator phenotype (CIMP), tobacco, GSTM1, CYP1A1, HPV and survival status." (PMID 26098903, 2015). "Using real time quantitative RT-PCR, the gene expression pattern of CYP1A1, CYP1A2, CYP1B1, CYP2E1, CYP2W1, CYP3A4, and CYP3A5 were analyzed in tumor and adjacent non-tumor tissues from 13 child RMS patients." (PMID 24699256, 2014). "Thirdly, the mean absolute values of total transcripts in tumor samples, is relatively low for CYP1A1, 1B1 in the HCC as well as for CYP1A1, 1B1 and 3A4 in the RCC." (PMID 24819355, 2014). "The CYP1A1 and CYP1A2 mRNA exhibited weak or undetectable expression in both normal (mean Ct>35) and tumor (mean Ct 35.9 and 34.4, respectively) tissues." (PMID 24699256, 2014). "In the present study, we compared the pattern expression of CYP1A1, CYP1A2, CYP1B1, CYP2E1, CYP2W1, CYP3A4 and CYP3A5 in paired tumor and normal tissue of child patients with RMS." (PMID 24699256, 2014). "The rest of the CYPs studied (CYP1A1, CYP1A2 and CYP1B1) showed similar mRNA relative expression levels between tumor and corresponding normal tissues." (PMID 24699256, 2014). "This corresponds to an approximate 65% overexpression of CYP1A1 and CYP1B1 mRNA respectively in the tumor tissues." (PMID 24358191, 2013). "Incubation of tumor microsomal protein with diosmetin and CYP1B1/CYP1A1 specific antibodies can improve the selectivity of the assay towards CYP1A1 and CYP1B1 isoforms." (PMID 24358191, 2013). "All of 20 matched tumor and normal bladder tissue pairs analyzed expressed detectable levels of CYP1B1 and CYP1A1 mRNA." (PMID 24358191, 2013). "Differential expression of CYP1A1 and CYP1B1 in various tumor types, compared to normal tissue has been demonstrated by several studies, thus highlighting the potential use of the two CYP1 isoforms in cancer prognosis." (PMID 24358191, 2013). "CYP1A1 and CYP1B1 mRNA showed statistically significant upregulation across the tumor counterpart in 13/20 pairs respectively, as determined by qPCR." (PMID 24358191, 2013).
tumor (continued). "For example, TSP1, CYP1A1, and GDF15 mRNA induction are most likely reflecting a direct inducing effect on the tumor cells, because elevated mRNA levels were also achieved in vitro in cell cultures where no other cell types were present." (PMID 20470445, 2010). "Patients with NSCLC tumor recurrence had a higher frequency of CYP1A1 editing compared with those without tumor recurrence." (PMID 40175891, 2025). "Altogether, our study demonstrated the successful development of pentyl-bearing PAIB-SOs in mice, as new CYP1A1-dependent prodrugs for BC treatments that efficiently decrease BC tumor growth and show no side effects at their pharmacological concentration." (PMID 40006600, 2025). "DIM-dependent induction of CYP1A1 promotes the formation of 2OHE1 rather than 4OHE1, which supports anti-inflammatory effects and protects against tumor formation." (PMID 37834026, 2023). "Participants in advanced stages, whether due to tumor size or regional metastasis, showed significant differences in the duration of tobacco use, FTCD, AUDIT score, and CYP1A1 expression when compared to patients in early stages." (PMID 35409669, 2022). "The first tumor-accelerated responses at 1 h after TPA treatment began with genes in “deregulated cellular metabolism”, with the up-regulation of CYP1a1 and CYP1b1, and with genes in “tumor-promoting inflammation”, with the up-regulation of prostaglandin E synthase in prostanoid biosynthesis." (PMID 35328637, 2022). "Bioprecursor and prodrug approaches that rely on tumour-expressed CYP1A1 and not AhR induction for bioactivation includes our own work focused on reengineered duocarmycin molecules." (PMID 33809117, 2021). "AF induced CYP1A1 and CYP1B1 gene expression in human tumor renal cell lines." (PMID 32443455, 2020). "Neither CYP1A1 nor CYP2W1 protein was detected in homogenates of MKN‐45 tumours recovered from vehicle‐treated mice." (PMID 31876059, 2020). "Repression of CYP1A1 in tumor cells was elicited by a macrophage-shaped tumor microenvironment rather than by direct tumor cell-macrophage contacts." (PMID 30615637, 2019). "Induction of CYP1A1 and CYP1B1 is known to bioactivate environmental toxicants into their ultimate carcinogenic epoxide and diol-epoxide intermediates, which can bind covalently to DNA forming DNA adducts and subsequent tumor initiation." (PMID 28103884, 2017). "Interestingly, the expression levels of CYP1A1 and CYP3A in tumor and cirrhotic liver tissues are decreased in comparison with those in normal tissues, which is consistent with the signature we observed after BPA exposure." (PMID 29027980, 2017). "Reduced biotransformation of MCA and tumor development in myeloid Hif-1αLysM−/− mice is thus explained by diminished ARNT expression and the subsequently reduced metabolic activation of PAHs by CYP1A1 and CYP1B1." (PMID 27015123, 2016). "Thus, the aim of the present study was to determine the mRNA expression pattern of seven representative CYPs (e.g., CYP1A1, CYP1A2, CYP1B1, CYP2E1, CYP2W1, CYP3A4, and CYP3A5) in paired tumor and normal tissue of childhood patients with RMS." (PMID 24699256, 2014). "The data show that cytotoxic effects of ellipticine in tumor tissues are dictated by (I) levels of CYP expression (and/or peroxidase expression); (II) levels of cytochrome b5 expression; and (III) its own potency to induce CYP1A1, CYP3A and cytochrome b5 in tumor tissues and cells." (PMID 25547492, 2014). "4/20 and 5/20 tumor tissues revealed significant downregulations of CYP1B1 and CYP1A1 mRNA respectively, whereas in patients 13 and 17 the expression levels of CYP1A1 mRNA between tumor and normal tissue did not reveal a significant change." (PMID 24358191, 2013). "Results were supported by differential gene expression in non-tumor lung tissue samples with down-regulation of CYP1A1 in never smokers and up-regulation in smokers from CYP1A1/A2 SNPs." (PMID 19479063, 2009).
tumor (continued). "In addition, among the LNCaP xenograft tumours we collected, both TDO2 and AhR proteins were significantly upregulated in tumours that recurred after castration compared with normal tumours, and the mRNA levels of TDO2, AhR, and CYP1A1 were also significantly elevated." (PMID 40759641, 2025). "Notably, the marked activation of CYP1A1, CYP1B1, and SLC16A6, coupled with the downregulation of tumour suppressors such as LINC01085 and CBS, underscores the potential of PM2.5 to promote oxidative stress, carcinogenesis, and therapy resistance in a mutation-dependent manner." (PMID 40559957, 2025). "Regardless of whether patients received combination therapy or not, the phenomenon of CYP1A1+ tumor cells gathering around CD8+CCL5+ lymphocytes was frequently observed." (PMID 39183447, 2024). "However, it should also be noted that the expression of CYP1A1 in the tumor tissues of a considerable number of patients was not lower or even higher than that in normal liver tissues." (PMID 39183447, 2024). "Moreover, estrogen metabolism catalyzed by CYP1A1 and CYP1B1 leads to the formation of reactive intermediates, such as E2-4-hydroxy derivatives and quinones, which bind to DNA, forming DNA adducts, the important event in tumor initiation." (PMID 39339278, 2024). "Interestingly, the analysis indicates that CYP1B1 is likely regulated by two different mechanisms because basal CYP1B1 expression is retained even in AhR-low tumours, a feature that is not evident for CYP1A1." (PMID 33809117, 2021). "Interestingly though, CYP1A1 repression in tumor cells induced by MΦ appeared to be independent of the exact MΦ phenotype." (PMID 30615637, 2019). "While downregulated CYP1A1 can reduce the production of ROMs, thus minimizing DNA and protein damage, the upregulation of GSTA2 may allow cytotoxic xenobiotics to accumulate, possibly triggering tumor development." (PMID 30428922, 2018). "CYP1A1 and CYP3A4 are capable of metabolizing a variety of carcinogens, such as polycyclic aromatic hydrocarbons, heterocyclic amines, nitrosamines, azo-dyes, and alkylating agents, and by doing so may produce active derivatives that lead to the tumor initiation." (PMID 29027980, 2017). "However, when the carcinogenic PAH and HAA (procarcinogen) are oxygenized by CYP1A1 and CYP1A2 to produce arene oxide, diolepoxide, and other electrophilic reactive species (ultimate carcinogen) that form DNA and protein adducts, they can result in tumor formation and toxicity." (PMID 27999293, 2016). "However, RES inhibits CYP1A1 and CYP1B1, but still showed no decrease in tumor multiplicity when applied with DMBA in our study." (PMID 23835587, 2013). "In addition selective overexpression of CYP1A1 and CYP1B1 may be utilized to target specific tumor types by the activation of non-toxic prodrugs that are selectively metabolized to cytotoxic products." (PMID 24358191, 2013). "CYP1A1 has been shown to be overexpressed in ovarian cancer cells and esophageal tumours, as opposed to normal cells and tissue, and CYP1B1 protein has been detected in a wide variety of tumours such as breast, brain, colon, and lung, whereas no protein was detected in corresponding normal samples." (PMID 18454852, 2008).
infection (22 papers, 2016 to 2025). The state of being infected such as from the introduction of a foreign agent such as serum, vaccine, antigenic substance or organism. "Changes in the expression levels of CYP1A1 caused by infections or inflammatory stimuli have been observed in various organs, including the liver, kidney, and brain." (PMID 29686530, 2018). "Total RNA extracted post-infection was analyzed by qRT-PCR to measure RNA levels of AhR, CYP1A1, and the viral nucleocapsid gene." (PMID 41150072, 2025). "We also analyzed the differential expression of JPH4 and CYP1A1 during the early stages of infection in iPMAs and PAMs." (PMID 41425566, 2025). "In macrophages, CYP1A1 can be induced by LPS exposure, where its expression continued to increase as infection progressed." (PMID 38990812, 2024). "Only 5 cellular genes (Cyp1a1, Ltf, Nr4a3, Per2 and Zbtb16) were significantly modulated on day 1 post-infection." (PMID 35812400, 2022). "Following infection of Caco-2 cells with C. albicans, the expression levels of proteins CYP1A1 and TTP decreased significantly, but the expression levels of p-MK2 increased (P < 0.01)." (PMID 35923391, 2022). "Infections or inflammatory stimuli can alter the expression of CYP1A1 in various organs of humans and animals." (PMID 29686530, 2018). "The expression of cytochrome P4501A1 (CYP1A1) enzyme is changed in various organs during the host response to inflammation or infection, leading to alterations in the metabolism of endogenous and exogenous compounds." (PMID 29686530, 2018). "We validated in two cell-lines (Caco-2 and HT-29) the changes in expression of a number of genes (MT1E, NPPB, NOTCH3, CYP26A1, HEY1 and CYP1A1) found to be differentially expressed using RNAseq following infection with C. concisus UNSWCD or BAA-1457." (PMID 27677841, 2016). "Furthermore, the infection led to the upregulation of CYP1A1 and CYP1B1 levels, which are downstream target proteins in AhR signaling." (PMID 40142473, 2025). "Cr infection significantly attenuated I3C-induced expression of Cyp1a1 mRNA." (PMID 33076301, 2020). "Following infection with feline enteric CoV (FECV), strain “München”, a significant activation of AhR and of its target CYP1A1, was observed." (PMID 40006982, 2025). "Accordingly, organs from mice infected with A. baumannii contained elevated levels of CYP1A1 protein, indicating that AHR is activated in vivo following infection with A. baumannii." (PMID 39261458, 2024). "Four genes were differentially expressed in all four infection groups, of which expression of PTGS2, IL8 and CYP1A1 were upregulated, while expression of C9orf169 was upregulated at 2 h post infection, but downregulated at the 6 h time point." (PMID 37193047, 2022). "FICZ treatment activated AHR-mediated signaling, as shown by the significantly enhanced level of CYP1A1 gene expression, and significantly increased the level of HIV-luc/NL4-3 infection (unpaired t test, P < 0.001)." (PMID 31848275, 2019). "Although treatment with FICZ changed several aspects of the immune response to infection, relative to the other three AHR ligands used, the fold induction of Cyp1a1 was much less." (PMID 29379138, 2018). "Interestingly, induction of CYP1A1 and TGFB expression that was also noted in the transcriptome data, was limited to infections with live NTHi." (PMID 38990812, 2024). "Moreover, a strong oxidative stress response in the form of increased expression of metallothioneins and other antioxidant enzymes, as well as the upregulation of xenobiotic metabolism (CYP1A1 and CYP1B1) were found following infection with C. concisus UNSWCD." (PMID 27677841, 2016). "Overexpression of CYP1A1 by Wnt5A may enhance erythromycin’s metabolism and thus affects its half-life leading to the persistence of infection and lack of drug efficiency." (PMID 34079452, 2021).
adenocarcinoma (8 papers, 2006 to 2021). A common cancer characterized by the presence of malignant glandular cells. "Further investigation is required to investigate if estrogen has a causal link to adenocarcinoma by promoting carcinogenesis through increased CYP1A1 or other related pathways." (PMID 16451726, 2006). "3-MC induced CYP1A1 mRNA in all the cell lines tested, while serum induced CYP1A1 expression in all the cell lines except the human HT29-D4 adenocarcinoma cell line." (PMID 21304969, 2011). "The very low frequent variant in the database CYP1A1 857 T > C (I286T), which was found only 2 times in thousands of human genomes, has been detected in exons 3–6 of the CYP1A1 gene in a non-smoker adenocarcinoma case." (PMID 28074113, 2017). "In one non-smoker adenocarcinoma patient, the rare CYP1A1 857 T > C (I286T) was identified." (PMID 28074113, 2017).
cardiovascular diseases (4 papers, 2016 to 2023). "Do the cardiotoxicity effects produced in the lack of CYP1A1 activity be a window for searching new therapeutic targets for cardiovascular diseases?" (PMID 28105425, 2016).
metabolic disease (3 papers, 2018 to 2025). A congenital disorder (due to inherited enzyme abnormality) or acquired (due to failure of a metabolically important organ) disorder resulting from an abnormal metabolic process. "The role of these genes in response to PA or cellular stress in vECs is unknown, although Cyp1a1 expression is induced by shear stress and Cfd has been implicated in several cardiovascular and metabolic diseases." (PMID 40913284, 2025). "We observed that smoking-DMS in CYP1A1 and NOTCH1 were significantly associated with measures of metabolic disease risk." (PMID 30342560, 2018).
bacterial diseases (2 papers, 2022 to 2025). "In this study, flumequine, an antibacterial agent used to treat bacterial diseases, tended to increase the expression of CYP1A1, CYP1B1, CYP2B4, CYP2F2, and CYP4B1 following administration at a 4× dose compared to a 1× dose." (PMID 41227456, 2025).
breast (2 papers, 2017). "Therefore, we hypothesized that the effect of certain dietary flavonoid subclasses on colorectal carcinogenesis may differ according to the variants in the CYP1A1 gene." (PMID 28273931, 2017).
gastrointestinal disease (2 papers, 2021 to 2022). A disease that occurs in the gastrointestinal system, excluding the hepatobiliary system. "Another substrate of CYP1A1 is the macrolide erythromycin used as an antiinfection agent or for gastrointestinal disease in ICUs." (PMID 34079452, 2021).
inflammation (1 paper, 2015). Aberrant reaction of the microcirculation characterized by movement of fluid and leukocytes from the blood into extravascular tissues. "Pulmonary Cyp1a1 enzyme activity was decreased in LPS/BaP-treated mice relative to BaP-treated mice suggesting that pulmonary inflammation impacted on BaP-induced Cyp1a1 activity in the lung." (PMID 25911668, 2015).
intestinal disorder (1 paper, 2023). A non-neoplastic or neoplastic disorder that affects the small or large intestine. "However, the direct role of CYP1A1 beyond intestinal disorders such as NEC are yet to be explored." (PMID 40625576, 2023).
peripheral neuropathy (1 paper, 2024). A disorder affecting the peripheral nervous system. "When we studied the polymorphisms of CYP1A1 (rs1048943) in response to chemotherapy, we observed that CYP1A1 variant allele showednegative association with peripheral neuropathy in BC-P when treated with paclitaxel based chemotherapy (OR=0.35, 95% CI: 0.15-0.84;p=0.019)." (PMID 40092865, 2024).
retinopathy (1 paper, 2014). "This situation can be explained by the significant decrease in Cyp1a1 expression under oxidative stress, which constitutes one of the stages of the pathogenesis of AMD and AMD-like retinopathy in OXYS rats." (PMID 25132985, 2014).
CYP1A1 also shares sentences with these, for which no sentence is quoted: lung squamous cell carcinoma (5 papers); chronic myeloid leukemia (3); myocardial infarction (3); Parkinson disease (3); cryptorchidism (2); glioblastoma (2); head and neck squamous cell carcinoma (2); Hearing Loss (2); Insulin resistance (2); invasive breast carcinoma (2); Micropenis (2); nasopharyngeal carcinoma (2); Nephropathies (2); rheumatoid arthritis (2); skin cancer (2); thyroid nodule (2); Abdominal obesity (1); acne (1); allergic disease (1); aortic aneurysm (1); aspergillosis (1); asphyxia (1); autoimmune hepatitis (1); Autoimmunity (1); benign breast disease (1); benign prostatic hyperplasia (1); bone disorder (1); Bowen disease (1); brain glioma (1); breast adenocarcinoma (1).
A further 65 diseases each share a sentence with CYP1A1 in 1 paper.